OTX1 (orthodenticle homeobox 1)
Diseases named in the same sentence as OTX1 in open-access papers (continued):
Sharing a sentence is not in itself a finding about the gene and the disease.
prostate carcinoma (3 papers, 2014 to 2025). A carcinoma that arises from epithelial cells of the prostate gland. "Our data suggest that rs721048 may be associated with prostate cancer through the disruption of the mechanism of action of certain tumor-specific enhancers causing the dysregulation of the expression of OTX1 and EHBP1 genes." (PMID 35176995, 2022). "It is important to note that the expression of OTX1 is also associated with prostate cancer risk." (PMID 35176995, 2022). "Due to the observation of OTX1 and EHBP1 expression in various tumor tissues across cancer types, we hypothesized that the rs721048 variant, through enhancer activation, might increase the risk of malignancies beyond prostate cancer." (PMID 40004500, 2025).
B-cell lymphomas (2 papers, 2015 to 2023). "While OTX1 expression has been described in small subsets of normal germinal center B-cells in addition to high levels in subsets of aggressive non-HL, OTX2 was detected neither in normal B-cells nor in B-cell lymphomas." (PMID 26406991, 2015).
colitis (2 papers, 2020 to 2021). Inflammation of the colon. "After DNBS-induced colitis, analogously to OTX1, up-regulation of OTX2 in the rat myenteric plexus was evidenced also for the transcript and protein, by means of qRT-PCR and western immunoblotting." (PMID 32095330, 2020). "After DNBS-induced colitis the number of myenteric neurons expressing OTX1 is highly upregulated both on site and distantly." (PMID 32095330, 2020). "These biomolecular data confirm that an experimentally-induced colitis may up-regulate both the transcript and protein of OTX1 in the myenteric plexus both on site and distantly from the injury." (PMID 32095330, 2020). "In the present study, we investigated possible changes in the expression of homeoprotein transcription factors, orthodenticle homeobox protein 1 and 2 (OTX1 and OTX2), in the rat myenteric plexus after an experimentally-induced colitis." (PMID 32095330, 2020). "In this study, we evaluated OTX1 and OTX2 expression in the rat small intestine and distal colon myenteric plexus after intrarectal dinitro-benzene sulfonic (DNBS) acid-induced colitis." (PMID 32095330, 2020). "In good agreement, in the present study we show a significant increase of both OTX1 and OTX2 mRNA and protein levels in LMMP preparations of the rat small intestine and distal colon myenteric plexus after DNBS-induced colitis." (PMID 32095330, 2020). "In our study, we aim for the first time to evaluate possible changes of OTX1 and OTX2 expression in rat colon myenteric ganglia, after dinitro-benzene sulfonic (DNBS) acid-induced colitis, by means of molecular biology and morphological approaches." (PMID 32095330, 2020). "Accordingly, in the present study, a substantial involvement of iNOS and nNOS in colitis-induced upregulation of OTX1 and OTX2, respectively, is suggested by the superimposition of OTX1 with iNOS and OTX2 with nNOS immunostaining, in myenteric ganglia of both regions studied." (PMID 32095330, 2020). "In order to confirm the immunofluorescence data reflecting an up-regulation of OTX1 and OTX2 in the rat small intestine and colon myenteric plexus after DNBS-induced colitis, we evaluated the levels of mRNA and proteins of both homeobox proteins in LMMP preparations." (PMID 32095330, 2020).
developmental delay (2 papers, 2014 to 2023). "Mutations in OTX1, including chromosomal deletions encompassing OTX1, cause developmental delay, short stature, autistic behavior, dysmorphic features, and microcephaly." (PMID 38094004, 2023).
Hematuria (2 papers, 2021 to 2025). The presence of blood in the urine. "Besides, OTX1 methylation combined with clinical variables can be used to construct hematuria prediction model." (PMID 34559577, 2021).
hypogonadism (2 papers, 2013 to 2014). A disorder characterized by decreased function of the gonads. "The Otx1 knockout mice also show transient hypogonadism, and their transient growth retardation is thought to be secondary to low levels of pituitary hormones." (PMID 24023893, 2013). "OTX1 deletion could affect neighboring genes, in particular the gene WDPCP in which mutations were associated with hypogonadism, cryptorchidism, micropenis, and renal abnormalities." (PMID 25203062, 2014). "Regardless, we cannot exclude the possibility that the hypogonadism and cryptorchidism present in some subjects may be secondary to a pituitary defect similar to that occurring in the Otx1 null mice." (PMID 25203062, 2014). "To date, three of six female patients reported with 2p15p16.1 microdeletions (not including OTX1) have GU defects, one presenting with hypogonadism and two with hydronephrosis." (PMID 25203062, 2014).
Intellectual disability (2 papers, 2014 to 2021). "The lack of BRPF1 can also lead to multiple gene (such as Robo3 and Otx1) transcription reduction, the loss of neuronal migration and neural tube closure, the control of transcriptional regulation, and it can cause neurodevelopmental disorders, which can result in intellectual disability." (PMID 33643973, 2021). "In an additional case, OTX1 is deleted in a boy with intellectual disability and cryptorchidism." (PMID 25203062, 2014). "The first description is of a boy and a girl with mild intellectual disability and no GU defects with OTX1 deleted only in the girl." (PMID 25203062, 2014).
Lung Squamous Cell Carcinoma (2 papers, 2021 to 2023). "CpG islands associated with MSX1 and OTX1 were methylated in the majority of lung squamous cell carcinomas, while the ones associated with RUNX1 were methylated in more than 80% of lung adenocarcinomas, being well known that hypermethylation of CpG islands is a signature of malignant progression." (PMID 34262872, 2021).
microcephaly (2 papers, 2014 to 2023). A congenital or acquired developmental disorder in which the circumference of the head is smaller than normal for the person's age and sex. "Despite the low prevalence of microcephaly in patients with OTX1 or OTX2 variants, it is worth focusing on these OTX genes as potential causal genes for microcephaly, given the severity of the brain phenotypes observed in mice." (PMID 38094004, 2023). "In another study, six out of seven patients with variable chromosomal deletion (OTX1 being the only gene deleted in every case) showed genitourinary defects, and two of these six had microcephaly." (PMID 38094004, 2023). "In this study, I focus on several homeobox genes (ARX, LHX2, MEIS2, NKX2-1, OTX1, OTX2, and PAX6) implicated in the pathogenesis of microcephaly." (PMID 38094004, 2023). "This decrease in unitary neuronal output by RGPs largely accounted for the microcephaly and reduced neocortical thickness observed in Otx1–/– animals." (PMID 25417155, 2014).
ovarian carcinoma (2 papers, 2023 to 2025). A malignant neoplasm originating from the surface ovarian epithelium. "Similarly, in ovarian cancer, a high OTX1 level has been associated with advanced disease stage and unfavorable prognosis." (PMID 37780815, 2023).
triple-negative breast carcinoma (2 papers, 2020 to 2025). An invasive breast carcinoma which is negative for expression of estrogen receptor (ER), progesterone receptor (PR), and human epidermal growth factor receptor 2 (HER2). "MIR100HG promotes the proliferation of nasopharyngeal carcinoma cells via the miR-136-5p/IL-6 axis and enhances the growth of triple-negative breast cancer cells through the miR-5590-3p/OTX1 axis." (PMID 40969769, 2025).
adenoma (1 paper, 2023). A neoplasm arising from the epithelium. "J ROC analysis for OTX1 predicting aberrant methylation in adenoma." (PMID 37779184, 2023).
brain cancer (1 paper, 2022). A primary or metastatic malignant neoplasm affecting the brain. "Few studies have linked OTX1 overexpression with tumorigenesis and growth in cancers, and to the best of our knowledge, it has not been yet reported as an epigenetic marker in brain cancers." (PMID 36551712, 2022).
colorectal adenoma (1 paper, 2023). An adenoma that arises from the colon or rectum. "Our results showed that all the genes of ZNF471, SND1, SPOCK1, FBLIM1, and OTX1 methylation with the area under receiver operating curve (ROC) more than 0.90 were significantly high in the colorectal adenoma and CRC compared with the normal group." (PMID 37779184, 2023). "Based on the results of the methylation chip of Illumina Infinium 450K detection and bioinformatic analysis, five hypermethylated genes, ZNF471, SND1, SPOCK1, FBLIM1, and OTX1, were selected for further investigation in the colorectal adenoma, CRC, and control normal tissues in our study." (PMID 37779184, 2023).
cryptorchidism (1 paper, 2014). The failure of one or both testes of a male fetus to descend from the abdomen into the scrotum during the late part of pregnancy. "Hypogonadism resulting from OTX1 haploinsuficiency could lead to micropenis and cryptorchidism in these patients." (PMID 25203062, 2014).
embryonic carcinoma (1 paper, 2018). "Luc-reporters containing CRMs bound by SOX2 specifically in the CNS were activated in an additive fashion by SOX2 and OTX1 misexpression in mouse embryonic carcinoma P19 cells." (PMID 29432416, 2018).
ganglioglioma (1 paper, 2018). A well differentiated, slow growing neuroepithelial neoplasm composed of neoplastic, mature ganglion cells and neoplastic glial cells. "In ganglioglioma controls, Tbr1 nuclear labelling of dysmorphic neurons was noted in one case; a variable proportion also showed cytoplasmic OTX1 positive labelling but more consistent labelling was observed with SOX2." (PMID 28833756, 2018). "The consistent expression of OTX1 in MVNT, appeared more pronounced than observed in ganglioglioma or the dysmorphic neurones of FCD 20 and could suggest that VC are derived from incomplete maturation or migration of progenitors destined for the deeper cortical layers." (PMID 28833756, 2018).
Hodgkins lymphoma (1 paper, 2022). A heterogeneous group of malignant lymphoid neoplasms of B-cell origin characterized histologically by the presence of Hodgkin and Reed-Sternberg (HRS) cells in the vast majority of cases. "Lastly, the Hodgkin lymphoma cell lines that showed no expression of orthodenticle homeobox 1 and 2 (OTX1/2) (e.g., OTX 1 and 2 negative) overexpressed ZHX1, correlating with the genomic amplification of the 8q24 locus, supporting the oncogenic potential of ZHX1 in Hodgkin lymphoma." (PMID 36232466, 2022).
laryngeal carcinoma (1 paper, 2024). Carcinoma that arises from the laryngeal epithelium. "Notably, circMYOF is overexpressed in the serum exosomes of patients with laryngeal cancer and promotes cell migration by regulating the miR-145–5p/OTX1 axis, thereby accelerating the progression of laryngeal cancer." (PMID 38933443, 2024).
lymph node metastasis (1 paper, 2020). "In the current study, we first confirmed that OTX1 was overexpressed in LSCC tissues, and that high OTX1 expression in LSCC was associated with lymph node metastasis and poor prognosis." (PMID 32838760, 2020). "The OTX1 expression in LSCC was significantly correlated with lymph node metastasis." (PMID 32838760, 2020). "In summary, our study demonstrated that OTX1 is highly expressed in LSCC and related with lymph node metastasis and poor prognosis." (PMID 32838760, 2020).
meningioma (1 paper, 2022). A generally slow growing tumor attached to the dura mater. "When considering mitotic activity in meningiomas, we found negative correlations with DNAm for ARHGDIA and DOK7 and positive correlations for ESRRG and OTX1 (both correlating with all proliferation indices)." (PMID 36551712, 2022).
non-Hodgkin lymphoma (1 paper, 2020). Distinct from Hodgkin lymphoma both morphologically and biologically, non-Hodgkin lymphoma (NHL) is characterized by the absence of Reed-Sternberg cells, can occur at any age, and usually presents as a localized or generalized lymphadenopathy associated with fever and weight loss. "Meanwhile, the activation of OTX1 expression occurs in aggressive non-Hodgkin lymphoma." (PMID 32838760, 2020).
Obesity (1 paper, 2018). Accumulation of substantial excess body fat. "Instead, our screen suggests that different nearby cis gene may be more fruitful for further functional follow up for obesity, namely ZCCHC8, VPS33A, RSRC2; SPDEF, NUDT3; SETD1, VKORC1; SGSM2, SRR; VASP, SIX5; OTX1; BANK1; ARIH1; ELL; CHST8, respectively." (PMID 29608557, 2018).
papillary thyroid carcinoma (1 paper, 2023). "This study significantly advances our understanding of OTX1's role in thyroid cancer, particularly papillary thyroid carcinoma (PTC)." (PMID 37780815, 2023). "Our study provides evidence for the oncogenic role of OTX1 in papillary thyroid carcinoma (PTC)." (PMID 37780815, 2023).
prostate adenocarcinoma (1 paper, 2022). "Further, OTX1 is one of several transcription factors involved in tumor-specific enhancer networks and it was found to be linked to active enhancers in prostate adenocarcinoma." (PMID 35176995, 2022).
tumor (23 papers, 2015 to 2026). "One study reported that overexpression of OTX‐1 is associated with tumor‐promoting effects in various malignancies." (PMID 38925618, 2024). "Analogously to what is observed in other neoplasms, OTX1 activity is associated with levels of miR-3196, a GC commonly downregulated microRNA, with the OTX1 3′-UTR (untranslated region) as a target." (PMID 38069286, 2023). "Tu and colleagues demonstrated for the first time that the overexpression of OTX1 in LSCC tumor samples is associated with lymph node metastasis and poor prognosis." (PMID 38069286, 2023). "Comparative analysis of ESCC and adjacent noncancerous tissues revealed that an increased expression of OTX1 in ESCC is associated with tumor size, lymph node metastases, and survival." (PMID 38069286, 2023). "KD and overexpression experiments in cell lines identify an association between OTX1 expression and motility, cell cycle progression and tumor growth in xenografts." (PMID 38069286, 2023). "Nevertheless, these findings highlight the prognostic significance of age, tumor characteristics, and OTX1 expression in PTC, providing valuable insights for risk stratification and treatment decision-making in clinical practice." (PMID 37780815, 2023). "In bladder cancer, OTX1 dysregulation has been linked to increased tumor cell proliferation and invasiveness." (PMID 37780815, 2023). "This is further corroborated by observations of elevated tumor weight in instances of OTX1 up-regulation." (PMID 41019508, 2026). "Immunofluorescence results indicated a significant increase in p-ERK1/2 expression in the tumor tissues of the OTX1 overexpression group." (PMID 41019508, 2026). "In vivo experiments showed that the overexpression of OTX1 promoted tumor growth and increased tumor volumes." (PMID 41019508, 2026). "The literature describes OTX1 overexpression in tumor tissues across various cancers, including colorectal, breast, bladder, thyroid, and cervical malignancy." (PMID 40004500, 2025). "Conversely, the overexpression of OTX1 enhances these processes in vitro and promotes tumor growth in vivo." (PMID 39331921, 2024). "Consistently, upon excising the xenografts, the OTX1-shRNA group exhibited a substantial reduction in tumor weight compared to the scrambled-shRNA group." (PMID 37780815, 2023). "In vivo xenograft experiments using nude mice corroborated the in vitro findings, demonstrating that silencing OTX1 significantly suppressed tumor growth in subcutaneous PTC xenografts derived from BCPAP and TPC cell lines." (PMID 37780815, 2023). "For instance, a DMR (chr2: 63,055,387—63,055,523) overlapping Orthodenticle Homeobox 1 (OTX1) gene was hyper-methylated in tumor tissues." (PMID 37936230, 2023). "Taken together, these findings suggest that OTX1 promotes cell proliferation and cell cycle progression in vitro as well as tumor growth in vivo." (PMID 37627900, 2023). "Immunohistochemistry (IHC) analysis of PTC tissues revealed a significantly higher OTX1 expression in certain tumor samples, indicating its potential as a prognostic biomarker in PTC." (PMID 37780815, 2023). "Through regulation of different pathways (CADM1, SOCS2, Smad7, OTX1), miR-424-5p can act to inhibit tumor progression." (PMID 35409396, 2022). "The results showed that OTX1 promoted cell growth and motility by regulating cell cycle in vitro, and promoted tumor growth in vivo." (PMID 34559577, 2021). "The expression of OTX1 in tumor tissues and para-cancerous tissues was evaluated by immunohistochemistry staining." (PMID 34559577, 2021). "Our study unveiled that miR-4269 exerted its tumor inhibitory effects on PC progression by modulation of ZEB1/OTX1 axis, which offered a new insight into the clinical treatment of PC patients." (PMID 32484209, 2020). "As expected, the OTX1 knockdown groups clearly showed reduced tumor growth and decreased tumor weight compared with those in the matched control groups." (PMID 32838760, 2020).